KCNK2 (potassium two pore domain channel subfamily K member 2)
Description:
K(+) channel that conducts voltage-dependent outward rectifying currents upon membrane depolarization. Voltage sensing is coupled to K(+) electrochemical gradient in an 'ion flux gating' mode where outward but not inward ion flow opens the gate. Converts to voltage-independent 'leak' conductance mode upon stimulation by various stimuli including mechanical membrane stretch, acidic pH, heat and lipids. Reversibly converts between a voltage-insensitive K(+) 'leak' channel and a voltage-dependent outward rectifying K(+) channel in a phosphorylation-dependent manner (By similarity). Homo- and heterodimerizes to form functional channels with distinct regulatory and gating properties (By similarity). In trigeminal ganglia sensory neurons, the heterodimer of KCNK2/TREK-1 and KCNK18/TRESK inhibits neuronal firing and neurogenic inflammation by stabilizing the resting membrane potential at K(+) equilibrium potential as well as by regulating the threshold of action potentials and the spike frequency (By similarity). At trigeminal A-beta afferent nerves, the heterodimer of KCNK2/TREK-1 and KCNK4/TRAAK is mostly coexpressed at nodes of Ranvier where it conducts voltage-independent mechanosensitive and thermosensitive currents, allowing rapid action potential repolarization, high speed and high frequence saltatory conduction on myelinated nerves to ensure prompt sensory responses (By similarity). In hippocampal astrocytes, the heterodimer of KCNK2/TREK-1 and KCNK1/TWIK-1 allows passive K(+) conductance under basal conditions, but changes ion selectivity and becomes permeable to L-glutamate and Cl(-) ions upon binding to G protein subunit GNG4 in stimulated astrocytes. Mediates rapid L-glutamate release in response to activation of G protein-coupled receptors, such as F2R and CNR1 (By similarity). In hippocampal pyramidal neurons, the homodimer of KCNK2/TREK-1 contributes to gamma-aminobutyric acid (GABA) B-induced slow inhibitory postsynaptic potential. Associates with AKAP5 and Gs-protein-coupled receptor B2AR at postsynaptic dense bodies and converts to a leak channel no longer sensitive to stimulation by arachidonic acid, acidic pH or mechanical stress, nor inhibited by Gq-coupled receptors but still under the negative control of Gs-coupled receptors (By similarity). Permeable to other monovalent cations such as Rb(+) and Cs(+) (By similarity). [Isoform 4]: Does not display channel activity but reduces the channel activity of isoform 1 and isoform 2 and reduces cell surface expression of isoform 2.
Synonyms: K2P2.1; TREK; TREK1; TREK-1; TPKC1; hTREK-1c; hTREK-1e
Tractability: Small molecule: an approved drug acts on it; a structure with a bound ligand is known; a high-quality ligand is known; it belongs to a druggable protein family. Antibody: UniProt places it where antibodies can reach, with high confidence; its Gene Ontology location is reachable by antibodies, with high confidence; UniProt predicts a signal peptide or a membrane-spanning region. PROTAC: a small molecule that binds it is known.
Target class: Two-pore domain potassium channel; Voltage-gated ion channel; Ion channel; Potassium channels
Gene: Protein-coding gene on chromosome 1 (215,005,775 to 215,237,090, forward strand). Ensembl gene ENSG00000082482.
Subcellular location: Cell membrane (Isoform 2); Cell membrane (Isoform 3); Endoplasmic reticulum membrane (Isoform 4); Cell projection, axon; Cell projection, dendrite; Postsynaptic density membrane; Cell membrane, sarcolemma
Pathways (Reactome):
Muscle contraction: Phase 4 - resting membrane potential
Neuronal System: TWIK related potassium channel (TREK)
Gene Ontology:
Molecular function: mechanosensitive potassium channel activity; identical protein binding; ligand-gated channel activity; outward rectifier potassium channel activity; potassium ion leak channel activity; protein heterodimerization activity; potassium channel activity
Biological process: cellular response to arachidonate; chloride transmembrane transport; detection of mechanical stimulus involved in sensory perception of touch; glutamate secretion; neuronal action potential; potassium ion transmembrane transport; regulation of synaptic transmission, GABAergic; cardiac ventricle development; cellular response to hypoxia; cochlea development; memory; negative regulation of cardiac muscle cell proliferation; negative regulation of DNA biosynthetic process; positive regulation of cellular response to hypoxia; response to axon injury; response to mechanical stimulus
Cellular component: plasma membrane; astrocyte projection; dendrite; endoplasmic reticulum membrane; node of Ranvier; postsynaptic density membrane; apical plasma membrane; axon; axon terminus; calyx of Held; cell surface; membrane; neuronal cell body; sarcolemma
Genetic constraint (gnomAD): Loss-of-function variants: 17 observed, 35.35 expected, observed/expected ratio (o/e) 0.48, 90% interval 0.33 to 0.72. The upper end of that interval is the gene's LOEUF score, 0.72, which puts it in group 2 of 6, group 1 being the genes least tolerant of losing a copy. Missense variants: 361 observed, 490.83 expected, observed/expected ratio (o/e) 0.74, 90% interval 0.67 to 0.8. Synonymous variants: 167 observed, 191.88 expected, observed/expected ratio (o/e) 0.87, 90% interval 0.77 to 0.99.
Homologues: Orthologues: chimpanzee KCNK2 (100% identical), macaque KCNK2 (100% identical), pig KCNK2 (99% identical), guinea pig KCNK2 (96% identical), rabbit KCNK2 (96% identical), mouse Kcnk2 (96% identical), rat Kcnk2 (96% identical), tropical clawed frog kcnk2 (82% identical), zebrafish kcnk2a (73% identical), zebrafish kcnk2b (61% identical), dog KCNK2 (28% identical), Caenorhabditis elegans twk-22 (23% identical), and 12 more. Paralogues in human: KCNK10 (59% identical), KCNK4 (35% identical), KCNK16 (22% identical), KCNK17 (21% identical), KCNK6 (21% identical), KCNK1 (21% identical), KCNK5 (20% identical), KCNK12 (20% identical), KCNK15 (19% identical), KCNK13 (19% identical), KCNK3 (19% identical), KCNK9 (19% identical), and 2 more.